NEMF (nuclear export mediator factor)
Description:
Key component of the ribosome quality control complex (RQC), a ribosome-associated complex that mediates the extraction of incompletely synthesized nascent chains from stalled ribosomes as well as their ubiquitin-mediated proteasomal degradation. Thereby, frees 60S subunit ribosomes from the stalled translation complex and prevents the accumulation of nascent polypeptide chains that are potentially toxic for the cell. Within the RQC complex, NEMF specifically binds stalled 60S ribosomal subunits by recognizing an exposed, nascent chain-conjugated tRNA moiety and promotes the recruitment of LTN1 to stalled 60S subunits. Following binding to stalled 60S ribosomal subunits, NEMF mediates CAT tailing by recruiting alanine-charged tRNA to the A-site and directing the elongation of stalled nascent chains independently of mRNA or 40S subunits, leading to non-templated C-terminal alanine extensions (CAT tails). Mainly recruits alanine-charged tRNAs, but can also other amino acid-charged tRNAs. CAT tailing is required to promote ubiquitination of stalled nascent chains by different E3 ubiquitin-protein ligases. In the canonical RQC pathway (RQC-L), CAT tailing facilitates LTN1-dependent ubiquitination by exposing lysine residues that would otherwise remain buried in the ribosomal exit tunnel (By similarity). In the alternative RQC pathway (RQC-C) CAT tailing creates an C-degron mainly composed of alanine that is recognized by the CRL2(KLHDC10) and RCHY1/PIRH2 E3 ligases, leading to ubiquitination and degradation of stalled nascent chains. NEMF may also indirectly play a role in nuclear export.
Synonyms: SDCCAG1; NY-CO-1; FLJ10051; RQC2; IDDSAPN
Tractability: PROTAC: ubiquitination databases record sites on it; its protein half-life has been measured.
Gene: Protein-coding gene on chromosome 14 (49,782,083 to 49,852,822, reverse strand). Ensembl gene ENSG00000165525.
Subcellular location: Cytoplasm, cytosol; Nucleus
Subcellular location (Human Protein Atlas): Cytosol; Nucleoplasm; Nuclear bodies
Pathways (Reactome):
Metabolism of proteins: Ribosome Quality Control (RQC) complex extracts and degrades nascent peptide
Gene Ontology:
Molecular function: alpha-aminoacyl-tRNA binding; ribosomal large subunit binding; tRNA binding
Biological process: CAT tailing; nuclear export; protein-containing complex assembly; rescue of stalled ribosome; ribosome-associated ubiquitin-dependent protein catabolic process
Cellular component: cytosol; cytosolic ribosome; RQC complex; nucleus
Genetic constraint (gnomAD): Loss-of-function variants: 49 observed, 90.53 expected, observed/expected ratio (o/e) 0.54, 90% interval 0.43 to 0.69. The upper end of that interval is the gene's LOEUF score, 0.69, which puts it in group 2 of 6, group 1 being the genes least tolerant of losing a copy. Missense variants: 767 observed, 871 expected, observed/expected ratio (o/e) 0.88, 90% interval 0.83 to 0.94. Synonymous variants: 293 observed, 290.91 expected, observed/expected ratio (o/e) 1.01, 90% interval 0.92 to 1.11.
Gene-disease validity (ClinGen):
ClinGen rates the evidence that NEMF causes each of these diseases.
intellectual developmental disorder with speech delay and axonal peripheral neuropathy (autosomal recessive): Strong.
Homologues: Orthologues: chimpanzee NEMF (99% identical), macaque NEMF (99% identical), dog NEMF (95% identical), pig NEMF (94% identical), rabbit NEMF (92% identical), guinea pig NEMF (92% identical), mouse Nemf (89% identical), rat AABR07064719.2 (87% identical), tropical clawed frog nemf (70% identical), Drosophila melanogaster Clbn (45% identical), Caenorhabditis elegans Y82E9BR.18 (36% identical).
Diseases named in the same sentence as NEMF in open-access papers:
NEMF is named in the same sentence as 31 diseases in open-access papers, as found by Europe PMC text mining. Sharing a sentence is not in itself a finding about the gene and the disease. The quoted sentences say what the papers report.
Intellectual disability (3 papers, 2019 to 2023). "Our results indicate that patients with NEMF variants can additionally manifest intellectual disability, most notably speech delay." (PMID 32934225, 2020). "Furthermore, recent studies show that NEMF variants are associated with neurological disorders including intellectual disability, suggesting a link between dysfunction of neuronal RQC and human neurological diseases." (PMID 36917672, 2023). "Many of these genes have been previously implicatedwith human phenotypes, including developmental delay (e.g. ASPM, AFF3 and MAPT) and intellectual disability (e.g. NEMF, PI4KA and KANSL1)." (PMID 31757203, 2019). "In addition, NEMF variants, which were hypothesized to reduce RQC functions, are associated with intellectual disability." (PMID 36917672, 2023).
motor neuron degeneration (3 papers, 2020 to 2025). "Recently, single nucleotide polymorphisms (R86S and R487G) in Nuclear Export Mediator Factor (NEMF) mouse models showed progressive motor neuron degeneration, characterized by hindlimb wasting and denervation of neuromuscular junctions." (PMID 40377023, 2025). "Here we show that three independently-generated mouse models with mutations in a different component of the RQC complex, NEMF/Rqc2, develop progressive motor neuron degeneration." (PMID 32934225, 2020).
developmental delay (2 papers, 2019 to 2020). "In a Saudi Arabian family (SAU1) with two individuals presenting with developmental delays, a homozygous frameshift variant in NEMF was identified (c.2871_2875dupTGTAG; p.(Asp959fs*2))." (PMID 32934225, 2020). "In a Persian family (IRN1), a proband presented with hypotonia, developmental delays and severe speech delay; WGS identified a homozygous frameshift variant in NEMF (c.2451delA; p.(Ser817fs*7))." (PMID 32934225, 2020). "In a Turkish family, (DEU1) with two individuals presenting with developmental delay and peripheral neuropathy in childhood, a homozygous nonsense variant in NEMF was identified (c.2014A > T, p.(Lys672*))." (PMID 32934225, 2020).
bladder cancer (1 paper, 2024). "The levels of RQC proteins ZNF598, NEMF, and ABCE1 induced by EME was decreased by co-treatment with CCCP in T24 and primary culture bladder cancer cells." (PMID 39315278, 2024).
glioma (1 paper, 2026). A benign or malignant brain and spinal cord tumor that arises from glial cells (astrocytes, oligodendrocytes, ependymal cells). "A murine GBM model exhibited analogous RQC pathway alterations, with increased NEMF and decreased ANKZF1 expression in transplanted SB28 gliomas compared to normal brain tissue." (PMID 38798583, 2026).
ovarian carcinoma (1 paper, 2025). A malignant neoplasm originating from the surface ovarian epithelium. "Dysregulation of NEMF has been implicated in various cancers, including colon cancer and ovarian cancer." (PMID 40875638, 2025).
sensorimotor peripheral neuropathy (1 paper, 2020). "A Caucasian proband (USA3-II:2) who presented with axonal sensorimotor peripheral neuropathy at 17 years of age harbored a de novo missense variant in NEMF (c.1658T > C, p.(Ile553Thr))." (PMID 32934225, 2020).
stomach cancers (1 paper, 2025). "The NEMF expression exhibits tissue-specific variability across cancer types: it is downregulated in most malignancies (e.g., brain, central nervous system, breast, colon, and stomach cancers) but shows distinct patterns in other contexts." (PMID 40875638, 2025).
cancer (5 papers, 2015 to 2026). A tumor composed of atypical neoplastic, often pleomorphic cells that invade other tissues. "In addition to cancer, NEMF has also been linked to neuromuscular diseases and contributes to the maintenance of cellular homeostasis and the coordination of cellular response to oxidative stress, RNA damage and DNA damage." (PMID 40875638, 2025). "Interestingly, RQC factors can display opposing functions in cancer development and suppression depending on specific circumstances, with some factors like ABCE1, ASCC3, and VCP suppressing cancer cell growth upon downregulation, while others like NEMF/Clbn and ZNF598 may promote it upon inhibition." (PMID 38798583, 2026). "The inhibition of ABCE1, ASCC3, and VCP has been shown to impede cancer cell proliferation and viability, while inhibiting NEMF/Clbn and ZNF598 may facilitate cancer cell growth and survival." (PMID 40785597, 2025).
neurological disorders (3 papers, 2021 to 2025). "Loss of Nemf also impairs axonal outgrowth and synapse development in cultured mouse primary cortical neurons and biallelic NEMF mutations have been identified in families with hereditary neurological disorders." (PMID 38949989, 2025). "Mutation of both GIGYF2 and RQC components, such as Listerin/LTN1 and nuclear export mediator factor (NEMF), cause neurological disorders in mice." (PMID 34502507, 2021).
neuromuscular disease (3 papers, 2020 to 2025). "Finally, we identify NEMF mutations expected to interfere with function in patients from seven families presenting juvenile neuromuscular disease." (PMID 32934225, 2020).
neurodegenerative disease (2 papers, 2024). A disorder of the central nervous system characterized by gradual and progressive loss of neural tissue and neurologic function. "First, taking advantage of two novel mouse models of NEMF neurodegeneration (NemfR86S and NemfR487G) that recapitulate many cellular and biochemical aspects of neurodegenerative diseases, we find an Importin-β-specific nuclear import block." (PMID 39312574, 2024). "Mutations in RQC factors such as Ltn1 and nuclear export mediator factor (NEMF) and ribosomal stalling in the brain triggered by the scarcity of brain-specific tRNAs cause neurodegenerative diseases." (PMID 38474243, 2024).
NEMF also shares sentences with these, for which no sentence is quoted: tumor (2 papers); adult-onset Still disease (1); Alzheimer disease (1); autism (1); colon cancer (1); epilepsy (1); Hypertension (1); keratosis (1); leukemia (1); lung carcinoma (1); mental disorder (1); metabolic disorder (1); neuropathy (1); peripheral neuropathy (1); personality disorder (1); pulmonary disorder (1); retinitis pigmentosa (1); schizophrenia (1); toxoplasmosis (1).